CXCR4 (C-X-C motif chemokine receptor 4)
Diseases named in the same sentence as CXCR4 in open-access papers (continued):
Sharing a sentence is not in itself a finding about the gene and the disease.
breast carcinoma (continued). "The CXCL12/CXCR4 signaling pathway plays an important role in the growth and angiogenesis of primary breast cancer." (PMID 37760498, 2023). "Exosomes released from CXCR4 (CXC motif chemokine receptor 4)/CD184-overexpressing breast cancer cells contained significant amounts of stemness-related markers and metastasis-related messenger ribonucleic acids (mRNAs)." (PMID 37456253, 2023). "In a mouse breast cancer model, vitamin D deficiency increases lung expression of CXCL-12; therefore, CXCR-4-positive tumor cells follow the CXCL-12 gradient." (PMID 37114140, 2023). "Breast cancer cells with high CXCR4 expression can metastasize to specific organs with CXCL12 chemotaxis, resulting in organ-specific metastasis." (PMID 35463082, 2022). "The CXCL12/CXCR4/ACKR3 cascade is reported to be involved in almost every aspect of breast cancer tumorigenesis." (PMID 36233192, 2022). "LMWH inhibited the interaction between CXCL12 and CXCR4, thereby reducing the metastatic spread of breast cancer cells in mice." (PMID 36296562, 2022). "These cells engage and activate CXCR4 expressed on the surface of breast cancer cells to promote tumor growth and invasiveness." (PMID 35565443, 2022). "MiR-139 upregulation repressed breast cancer stem cells with mesenchymal characteristics and reduced cell invasiveness by downregulating the CXCR4/p-Akt axis." (PMID 35804829, 2022). "CXCR4 plays a role in the growth and metastasis of breast cancer via its ligand CXCL12/SDF-1, which activates mTOR to promote the epithelial–mesenchymal transition (EMT), and is therefore important in metastasis." (PMID 35754051, 2022). "Relevant studies have pointed out that the activation of SDF-1α/CXCR4 axis in either human breast cancer cell lines or prostate cancer cell lines promotes VEGF secretion to participate in tumor angiogenesis." (PMID 36131788, 2022). "RNA-sequencing data analysis on the human breast cancer cell line MDA-MB-231 has shown that CXCR4, PLLP, VCAM1, SLC7A11, SLC8A2, and TNFSF4 genes are highly over-expressed in brain metastasis." (PMID 35045088, 2022). "As is reported, CXCR4 is highly expressed in breast cancers, with the ligand CXCL12 showing the highest levels of expression in the organ where cancer metastases first occur." (PMID 35630915, 2022). "Another study also showed that PDGFD can activate CXCR4 to promote lymphatic metastasis in breast cancer." (PMID 35509844, 2022). "We used luciferase complementation in cell-based assays and a tumor xenograft model of breast cancer in NSG mice to quantify how CXCR4 and ACKR3 change protein interactions in the β-arrestin-ERK-PKM2 pathway." (PMID 35681470, 2022). "CXCR4 also promotes breast cancer metastasis to organs (bone, liver and lung) where there is an abundance of its ligand, SDF-1." (PMID 36140541, 2022). "The chemokine receptor CXCR4 is expressed in many breast cancers, and has an important role in the migration, invasiveness, metastasis, and proliferation of tumors." (PMID 35565232, 2022). "We have previously reported that JUNB and CXCR4 are overexpressed in circulating and disseminated tumor cells from breast cancer patients and are correlated with worse survival." (PMID 36612166, 2022). "In a mouse model of breast cancer, this nano-emulsion inhibited CXCR4 and STAT3 expression with significant anti-metastatic activity." (PMID 35893797, 2022). "We have previously also shown that DTCs isolated from the bone marrow of early, non-metastatic, breast cancer patients also express high levels of JUNB and CXCR4, with their expression being similar or higher to other breast cancer cell lines." (PMID 36612166, 2022).
breast carcinoma (continued). "Overexpression of CXCL12 can promote the growth of human breast cancer cells, exacerbating nasopharyngeal carcinoma cell migration and invasion by binding to its receptor CXCR4." (PMID 35647303, 2022). "CXCR4 is found in a variety of human cancers, such as breast cancer, prostate cancer, and oral squamous cell carcinoma, and CXCR4 expression is also found in ovarian cancer tissues and cell strains." (PMID 35545781, 2022). "In EC, there are inconclusive works regarding CXCR4 expression as a possible prognostic factor, similar to findings in breast cancer, in which CXCR4 expression shows a different prognosis depending on the tumor subtype." (PMID 35884987, 2022). "A few CXCR4 antagonists have been investigated in breast cancer models and have shown promising results." (PMID 36140541, 2022). "The CXCL12/CXCR4 axis plays a critical role in directing the metastasis of CXCR4+ cancer cells to organs that express high CXCL12 levels in breast cancer." (PMID 35053615, 2022). "We find that growth factor receptors and CXCR4/ACKR3 chemokine receptors cooperate to integrate signals from the tumor microenvironment in certain breast cancer subtypes." (PMID 36233192, 2022). "In particular the CXCR4/CXCL12 axes has been reported to control breast cancer metastasis and the involvement of CAFs." (PMID 36588678, 2022). "It has been found that CXCR4, also known as fusin, is necessary for breast cancer cells migration towards tissues that present a high quantity of its specific ligand—cytokine SDF1 (CXCL12)." (PMID 36230523, 2022). "TBMS I can also inhibit the invasion and metastasis of breast cancer MDA-MB-231 cells by downregulating the expression of CXCR4 or interrupting CXCL12-CXCR4 cell signal pathway." (PMID 36160391, 2022). "Chemotaxis, especially for the CXC chemokine receptor-4 (CXCR4) was proved to exert a pivotal role in regulating the metastasis of breast cancer to bone." (PMID 35685372, 2022). "The chemokine receptor CXCR4 not only plays a key role in tumorigenesis and cancer progression, but it is also an effective prognostic factor for breast cancer." (PMID 35992864, 2022). "Protein-protein interaction (PPI) analysis revealed seven shared (PLCB1, FPR1, FPR2, CX3CL1, GABBR2, GPR37, and CXCR4) hub genes between brain and lung metastasis in breast cancer." (PMID 35045088, 2022). "The pentacyclic triterpene polyformic acid (PA), obtained from Euscaphis japonica, inhibits the transcription and expression of the CXCR4 protein in breast cancer cells and suppresses CXCL12-induced cell invasion." (PMID 35893797, 2022). "Dysregulated activation of CXCR4 has attracted considerable attention in cancer research; CXCR4 expression promotes survival of breast cancer cells and is required for the generation of migrating cancer stem cells." (PMID 34927784, 2022). "The importance of this mechanism has been inferred in models of pancreatic and breast cancer in which inhibition of CXCR4 using a clinically approved inhibitor (AMD3100) increased intratumoural T cell accumulation and response to checkpoint inhibition." (PMID 35977489, 2022). "Previous studies have shown that high expression of SDF-1/CXCR4 is correlated with poor survival in various tumors, such as colorectal cancer, prostate cancer, pancreatic cancer, and breast cancer." (PMID 36341391, 2022). "Earlier studies of our group in CTCs and disseminated tumor cells (DTCs) from breast cancer patients identified a new pair of biomarkers, namely the C-X-C motif chemokine receptor 4 (CXCR4) and the transcription factor JUNB." (PMID 36612166, 2022). "CXCR4 promotes breast cancer growth in three main ways: promoting angiogenesis, participating in the signal pathway of cell proliferation, and recruiting immune cells." (PMID 35992864, 2022). "Insulin‐like growth factor I and the chemokine CXCL12 and its receptor, CXCR4, are important for directional migration of breast cancer cells." (PMID 35520391, 2022).
breast carcinoma (continued). "Among these, the interaction between chemokine CXCL12 and its receptor CXCR4 is the basis of the metastasis of breast cancer." (PMID 36296562, 2022). "Our studies have shown that JUNB and CXCR4 are significantly overexpressed in CTCs isolated from metastatic breast cancer patients compared to normal donors’ and patients’ peripheral blood mononuclear cells (PBMCs)." (PMID 36612166, 2022). "We have investigated in cell models representative of the major subtypes of breast cancer (BC) the interplay between the chemokine CXCL12/CXCR4/ACKR3 and EGF receptor (EGFR) family signaling cascades." (PMID 36233192, 2022). "AhR–dependent mechanisms for the inhibition of breast cancer by AhR agonists are variable and include the downregulation of multiple genes/gene products such as CXCR4, MMPs, CXCL12, SOX4 and the modulation of microRNA levels." (PMID 36428667, 2022). "(2018) reports that TQ via inhibition of the chemokine receptor type 4 (CXCR4) signaling pathway suppressed osteolytic bone metastasis of breast cancer." (PMID 35236304, 2022). "A study reported that decreased CTNND1 expression is associated with bone metastasis of triple-negative (TN) breast cancer and is involved in EMT and bone homing, by upregulating CXCR4 through the activation of the PI3K/AKT/HIF-1α pathway." (PMID 36497209, 2022). "By secreting CXCL12, CAFs attract conventional CD4+ T cell migration through its receptor-CXCR4 and promotes their differentiation into Foxp3+ regulatory T cells to create an immunosuppressive environment in human breast cancer." (PMID 35853880, 2022). "C-X-C chemokine receptor type 4 (CXCR4) (also known as CD184) is a diagnostic marker in several cancers, including breast cancer." (PMID 35250573, 2022). "Breast cancer cells enter bone sinusoidal niches via E-selectin contacts and are anchored by stromal cell-derived factor 1/C-X-C chemokine receptor type 4 (SDF1/CXCR4) interactions to develop dormant micrometastases." (PMID 36497322, 2022). "Accordingly, MDA-MB-231 breast cancer cells present a uniquely suitable model system for investigating the involvement of CXCR4 and CXCR3 receptors in the CXCL4–CXCL12 heterodimer signaling." (PMID 36229490, 2022). "During homing, the CXCR4 expressed by HSCs and breast cancer cells binds to the CXC chemokine ligand 12 (CXCL12) expressed by bone marrow stromal cells, such as osteoblasts, endothelial cells, and fibroblasts, to retain HSCs or tumor cells in the bone marrow." (PMID 36497209, 2022). "In this respect, inhibition of DPP4 has been reported to accelerate EMT and breast cancer metastasis via CXCL12/CXCR4/mammalian target of rapamycin (mTOR) signaling." (PMID 35053615, 2022). "Interference with CXCR4 expression using CXCR4 antagonist or lentivirus shRNA can effectively inhibit tumor cell proliferation and invasion in breast cancer, human hilar cholangiocarcinoma, laryngeal squamous carcinoma, and esophageal carcinoma." (PMID 35702353, 2022). "CXCR4 inhibitors also reduce myofibroblast content in all breast cancer subtypes, but only decrease angiogenesis in HER2 enriched breast cancer." (PMID 35754051, 2022). "This is corroborated by the finding that the CXCL12/CXCR4 pathway mediates CAF-dependent immunosuppression in a fibrotic breast cancer model." (PMID 36568151, 2022). "In preclinical animal models of metastatic prostate and breast cancer, accumulating evidence supports the roles of CXCR4 and E-selectin in driving cancer cell dissemination in the BM, where they form metastases." (PMID 36568151, 2022). "Nevertheless, it has been shown that CXCR4 expression was agumented in both lung and brain metastases induced by breast cancer." (PMID 35045088, 2022). "Previous studies have established that CXCR4 is required for breast cancer cell proliferation or survival, and CXCR4 inhibitors will improve the treatment of primary and metastatic breast cancer." (PMID 35630915, 2022).
breast carcinoma (continued). "CXCR4 has a fundamental role in tumor development and progression, and in the metastatic spread of mammary cancer." (PMID 36288156, 2022). "Study of breast cancer suggested that FOXP3 function as a key tumor suppressor through the up-regulation of CXCR4 and down-regulation of CXCL12, which thereby stimulate cell migration." (PMID 33869044, 2021). "One of the advantages of these drugs is their ability to decrease drug resistance—e.g., to tamoxifen by CXCR4 antagonists in breast cancer." (PMID 33467722, 2021). "Taking into account these affirmations, it will be very interesting to assess the role of NANOG and CXCR4 in other cancer cell lines apart from glioblastoma, like breast cancer cells." (PMID 34638956, 2021). "It was already demonstrated that the SDF-1α receptor, CXCR4, participates in the homing of breast cancer cells, mainly in the bones and liver." (PMID 33919589, 2021). "CXCR4 is expressed in 67% of breast cancer cells, with a level double of that in normal breast tissues." (PMID 33986665, 2021). "In a breast cancer xenograft model, the CXCR4-specific inhibitor AMD3100 successfully mobilized dormant tumor cells out of the perisinusoidal niche of the BM, as demonstrated with real-time in vivo imaging." (PMID 33287630, 2021). "As well as their possible use in the diagnosis and prognosis of breast cancer recurrence, it has been shown that blocking the CXCR4/SDF-1α axis inhibits the growth of breast cancer in vivo and in vitro." (PMID 33919589, 2021). "In breast cancer brain metastases, CXCR4 is upregulated in microglia, which supports the invasion of breast cancer cells into the brain." (PMID 33466236, 2021). "RT-qPCR confirmed a significant reduction in the levels of p44/42 MAPK and PI3K showing the importance of receptor CXCR4 on breast cancer cell growth." (PMID 35111484, 2021). "The CXCL12/CXCR4 axis plays an important role in directing CXCR4-overexpressed breast cancer cells’ metastasis to organs that express high levels of CXCL12, including bone marrow." (PMID 34503103, 2021). "One study showed that knockdown of WWP1 elevated the expression of CXCR4 in MDA-MB-231 breast cancer cells." (PMID 34226507, 2021). "Chemokine receptors CXCR4 and CCR7 have been shown to be linked to the metastatic spread of breast cancer, however, their precise function and underlying molecular pathways leading to the acquisition of the pro-metastatic properties remain poorly understood." (PMID 34685420, 2021). "This has limited our understanding of miRNA function in BCSC processes through which CXCR4 increases the progression of breast cancer." (PMID 34070538, 2021). "We next assessed the effect of CXCR4 knockdown expression in THP-1 macrophage cells on the activation of oncogenic MAPK pathway in breast cancer cells (MCF7)." (PMID 35111484, 2021). "Inhibition of CXCR4 with AMD3100 resensitizes metastatic breast cancer to ICB by decreasing desmoplasia and thus reprogramming the immunosuppressive TME of metastases." (PMID 34112258, 2021). "In summary, WWP1 govern CXCL12-mediated lysosomal degradation of CXCR4, leading to regulation of cell migration and bone metastasis in breast cancer." (PMID 34226507, 2021). "The study demonstrates the role of CXCR4 on breast cancer cell migration through TAM-cancer cell crosstalk." (PMID 35111484, 2021). "This receptor is reported to be actively involved in breast cancer bone metastasis by directing the CXCR4-positive cancer cells to organs that express high levels of CXCL12, such as bone marrow." (PMID 34503103, 2021). "In the current study, we explored the preferential role of miR-139 in interfering with breast cancer cell stemness by repressing the expression of CXCR4 protein." (PMID 34070538, 2021). "For examples, breast cancer patients with high levels of CXCR4 were found to have more extensive metastasis to lymph nodes and significantly reduced disease-free survival and overall survival." (PMID 33986665, 2021).
breast carcinoma (continued). "In the follow‐up study, we will investigate the effects of STAT3 signal pathway and CXCR4 on the development and metastasis of breast cancer at the animal level." (PMID 33955151, 2021). "CXCR-4 overexpression is correlated with poor prognosis in a broad spectrum of cancers, including colorectal cancer, melanoma, breast cancer, and prostate cancer." (PMID 34069563, 2021). "For example, CXCR4 overexpression has been identified as an adverse prognostic factor in breast cancer." (PMID 34771622, 2021). "Sphere formation, a routinely used technique to measure stemness and self-renewal, was used to show that CXCR4 overexpressing breast cancer cells had a higher self-renewal capacity when cultured in hypoxia." (PMID 33530455, 2021). "Hereby, we conducted overexpression of miR-139 to reduce BCSC genesis by down-regulating CXCR4/p-Akt axis, leading to decreased invasion and migration abilities of breast cancer cells." (PMID 34070538, 2021). "Quercetin and niclosamide are Wnt inhibitors that also have been shown to reduce CXCR4 expression in breast cancer stem cells and in retinal microvascular pericytes." (PMID 33671498, 2021). "Metastatic breast cancer cells express high levels of CXCR4; its ligand CXCL12 is highly secreted by stromal cells within these tissues." (PMID 34427969, 2021). "For example, CXCR4 facilitates the binding of breast cancer cells to endothelial cells at metastatic sites through a mechanism similar to that observed with leukocyte intra- and extravasation." (PMID 34830776, 2021). "We showed that this effect is achieved through the cross-talk between macrophages and breast cancer cell lines, where expression of CXCR4 in macrophages appears to be crucial for breast cancer cell migration." (PMID 35111484, 2021). "In breast cancer cells, chronic hypoxia increases CXCR4 expression independently of HIF-1, depending only on NF-κB." (PMID 33467722, 2021). "Previous studies have demonstrated that POU1F1/CXCL12/CXCR4 axis contributes to macrophage recruitment and polarization, thereby promoting breast cancer metastasis." (PMID 33927188, 2021). "Variations in CXCL12 expression levels are regulated in part by MSCs, and, accordingly, when CXCL12, CXCR4, or ER were blocked in a human breast carcinoma cell model, MSC-induced proliferation and migration were significantly decreased." (PMID 33530455, 2021). "Oppositely, cultivation of breast cancer cells with CXCR4 antagonist, AMD3100, sensitized mesenchymal stem cells to cytotoxic drugs and reduced tumor metastatic burden." (PMID 34070538, 2021). "Our data showed that miR-139 inhibits breast cancer cell stemness by directly targeting CXCR4 at the molecular and cellular levels as well as the results from in vivo mouse xenotransplantation assay." (PMID 34070538, 2021). "CXCR4 induces breast cancer metastases by binding to its ligand stromal cell-derived factor-1α (SDF-1), which is overexpressed in the bone marrow, liver, lung, and breast tumors sites." (PMID 33747948, 2021). "This study demonstrates that the RhoA or RhoC/YAP pathway accelerated tumor metastasis via increased expression of RHAMM and CXCR4 in melanoma and breast cancer cells." (PMID 33406809, 2021). "E5 was able to bind specifically to the 4T1 breast cancer line, inhibit migration by reducing CXCR4 expression." (PMID 34884588, 2021). "Overexpression of miR-139 down-modulated CXCR4/p-Akt axis to attenuate invasion and migration of human breast cancer stem cells both in vitro and in vivo." (PMID 34070538, 2021). "Preclinical studies of CXCR4 inhibitors have demonstrated its ability to attenuate the proliferation and metastasis of breast tumors; AMD3100 is a CXCR4 antagonist that decreases lung metastases in breast cancer." (PMID 33747948, 2021). "CXCR4 has a clear suggestive effect on breast cancer metastasis and prognosis, and is highly expressed in a variety of tumor cells and involved in chemotaxis, invasion, angiogenesis, and cell proliferation." (PMID 34198652, 2021).